TIGIT (T cell immunoreceptor with Ig and ITIM domains)
Diseases named in the same sentence as TIGIT in open-access papers (continued):
Sharing a sentence is not in itself a finding about the gene and the disease.
B cell lymphoma (4 papers, 2020 to 2025). "Prior studies of CD19-CAR-T therapy for B cell lymphoma demonstrated elevated TIGIT expression in host T cells at relapse, and high TIGIT expression in CD19-CAR-T cells in vivo was linked to greater exhaustion and poorer prognosis." (PMID 41419632, 2025). "As PD-1 or TIM-3 are co-expressed by TIGIT-positive T cells, targeting TIGIT could be an additional mechanism to avert exhaustion of T cells in B-cell Non-Hodgkin Lymphoma (B-NHL)." (PMID 32117298, 2020). "In non-Hodgkin B cell lymphomas, PD1- and TIGIT-expressing intratumoral T cells were shown to mark dysfunctional or exhausted effector T cells." (PMID 32188505, 2020).
chronic hepatitis (4 papers, 2019 to 2024). An active inflammatory process affecting the liver for more than six months. "Collectively, these results revealed that the immune-tolerant HBs-tg mice develop chronic hepatitis as result of TIGIT blockade or deficiency." (PMID 30644386, 2019). "TIGIT blocking or deficiency in HBsAg transgenic mice leads to chronic hepatitis and fibrosis, along with the emergence of functional HBsAg-specific cytotoxic T lymphocytes (CTLs), suggesting the breakdown of adaptive immunotolerance by TIGIT blockade or deficiency." (PMID 37056774, 2023). "TIGIT blockade or deficiency leads to chronic hepatitis and fibrosis, along with the emergence of functional HBsAg-specific cytotoxic T lymphocytes (CTLs), suggesting adaptive immune tolerance could be broken by TIGIT blockade or deficiency." (PMID 30644386, 2019). "In hepatitis B surface antigen (HBsAg) transgenic mice, TIGIT blockade leads to emergence of HBsAg-specific T cells, chronic hepatitis and progression to HCC, suggesting a role for TIGIT in maintaining immune tolerance to HBsAg in this model." (PMID 37056774, 2023). "TIGIT blocking in HBsAg transgenic mice, whose adaptive immune system is tolerant to HBsAg, drives inflammation, chronic hepatitis and promotes HCC, along with the emergence of functional HBsAg-specific CTLs." (PMID 37056774, 2023). "The kinetics of HBsAg-specific CTLs in the progression of chronic hepatitis to HCC showed that persistent TIGIT blockade induced a relatively high ratio of HBsAg-specific CTLs in the liver." (PMID 30644386, 2019). "After weekly injections of the anti-TIGIT mAb, HBs-tg mice developed chronic hepatitis, as evidenced by gradually increased ALT levels that were significantly higher than those in rat IgG-treated HBs-tg mice." (PMID 30644386, 2019). "In contrast to the observations in HBs-tg mice, TIGIT blockade failed to increase ALT levels and induce liver injury in HBs-tg Rag1−/− mice, suggesting a critical role of adaptive immunity in mediating TIGIT blockade-induced chronic hepatitis." (PMID 30644386, 2019). "TIGIT blockade or deficiency specifically reverses hepatic CD8+ T cell tolerance to HBsAg and therefore results in chronic hepatitis in HBs-tg mice." (PMID 30644386, 2019). "The slopes of CXCL9, CXCL10, CXCL11, and TIGIT were higher in T cells of chronic hepatitis patients than in those of patients with HBeAg+ chronic infection and HBeAg− chronic infection, indicating that the expression of these genes was increased in the corresponding cell types." (PMID 39135698, 2024). "TIGIT blockade or TIGIT deficiency could break CD8+ T cell tolerance to the viral antigen in HBs-tg mice, leading to chronic hepatitis and fibrosis." (PMID 30644386, 2019). "Having demonstrated TIGIT blockade-induced chronic hepatitis, we next sought to investigate whether CD8+ T cells break immune tolerance to HBsAg in our models." (PMID 30644386, 2019). "To further confirm the inhibition of chronic hepatitis by TIGIT, we crossed HBs-tg mice with Tigit−/− mice to obtain HBs-tg Tigit−/−mice." (PMID 30644386, 2019). "Moreover, our findings also highlighted an important contribution of the co-inhibitory receptor TIGIT to HBV tolerance, which works as a safeguard keeping immune homeostasis to prevent chronic hepatitis and HCC initiation." (PMID 30644386, 2019).
non-Hodgkin lymphoma (4 papers, 2021 to 2025). Distinct from Hodgkin lymphoma both morphologically and biologically, non-Hodgkin lymphoma (NHL) is characterized by the absence of Reed-Sternberg cells, can occur at any age, and usually presents as a localized or generalized lymphadenopathy associated with fever and weight loss. "In addition, CAR T-cell dysfunction associated with TIGIT expression contributed to poor responses in patients with relapsed or refractory non-Hodgkin’s lymphoma." (PMID 41394877, 2025). "TIGIT was just reported to be a novel marker expressed on CD8 CAR T cells and associated with CAR T-cell exhaustion in patients with non-Hodgkin’s lymphoma." (PMID 36163179, 2022).
ovarian tumors (4 papers, 2020 to 2025). "Curiously, CD8+ T cells infiltrated ovarian tumors have high TIGIT expression as shown in this paper, which may suggest ovarian tumors are a potential target for combination anti-LAG3 and anti-TIGIT therapy." (PMID 38086828, 2023). "While PD-1 and CTLA-4 blockade has revolutionized treatment in some malignancies, ovarian tumors frequently deploy multiple redundant checkpoint pathways, including TIM-3, LAG-3, and TIGIT, to evade immune attack." (PMID 40643516, 2025). "The ovarian tumors showed high gene expression of LAG3 and HAVCR2 (TIM3) and enhanced levels of TIGIT and CTLA4 in recurrent tumors compared to primary tumors." (PMID 33352957, 2020). "Moreover, combination therapies including anti-TIGIT and anti-PD-L1 synergize to enhance cytolytic CD8+ T cell activity which could be used to target ovarian tumors of the infiltrated subtype to alleviate exhaustion and immunosuppression." (PMID 38086828, 2023).
preeclampsia (4 papers, 2021 to 2025). Preeclampsia is a hypertensive disorder of pregnancy that is characterized by new-onset hypertension with proteinuria presenting after 20 weeks of gestation, and depending on mild or severe forms may initially present with severe headache, visual disturbances, and hyperreflexia. "Dysregulation of immune checkpoint pathways, like the TIGIT/CD226 axis, has been implicated in complications such as recurrent implantation failure and preeclampsia, suggesting a role for checkpoint modulation in therapeutic strategies." (PMID 39796279, 2025). "The CD226/TIGIT MFI ratio on the surface of the NK cell subpopulations showed a significant decrease in all the investigated NK subpopulations in EO preeclampsia compared to the healthy controls." (PMID 39125946, 2024). "A recent study by our group examined the TIGIT, CD226, CD112, and CD155 immune checkpoint molecules in the peripheral blood mononuclear cells of women diagnosed with early-onset preeclampsia." (PMID 39125946, 2024). "We assume that immune checkpoint molecules, including TIGIT/CD226/CD112/CD155, have an essential role in the regulation of the Th1 predominance, which is initiated by intrinsic factors released by the poorly developed placenta during EO preeclampsia." (PMID 34829838, 2021). "Similar to TIGIT, the expression level of the activating immune checkpoint receptor CD226 was also significantly lower by CD3+ T-, CD4+ T, CD8+ T, and NKT-like cells in women diagnosed with EO preeclampsia compared to the healthy pregnant cohort." (PMID 34829838, 2021). "Examination of the NKT cell subpopulation significantly elevated frequencies were measured in TIGIT+/CD226− and TIGIT−/CD226− subsets in EO preeclamptic cohort compared to healthy cohort; however, the frequency of the TIGIT−/CD226+ subpopulation was significantly decreased in EO preeclampsia." (PMID 34829838, 2021). "Moreover, there is no available information about the TIGIT, CD226, CD112, or CD155 immune checkpoint molecules in any context of preeclampsia." (PMID 34829838, 2021).
triple-negative breast carcinoma (4 papers, 2021 to 2025). An invasive breast carcinoma which is negative for expression of estrogen receptor (ER), progesterone receptor (PR), and human epidermal growth factor receptor 2 (HER2). "Our research focused on investigating the role of CD155/TIGIT checkpoints in the progression of triple-negative breast cancer (TNBC)." (PMID 38216949, 2024). "Our data showed that Vγ9Vδ2 T cells in triple-negative breast cancer patients had exhausted phenotype with increased PD-1, TIGIT, and Tim-3 expression and reduced cytokine production." (PMID 34381711, 2021). "In triple-negative breast cancer, the TIGIT/CD155 pathway was also found to inhibit PI3K, p-AKT, and p-mTOR expression, reducing glucose uptake and lactic acid production in CD8+ T cells, leading to CD8+ T cell activation and impairment of effector functions in the tumor microenvironment." (PMID 41024301, 2025). "Moreover, TIGIT overexpression was also observed in triple-negative breast cancer (TNBC) than none-TNBC samples." (PMID 33721026, 2021).
uveitis (4 papers, 2018 to 2022). An inflammatory process affecting a part of or the entire uvea. "TIGIT+ Tregs have been implicated in uveitis remission, given the correlation between TIGIT expression and remission in uveitis patients." (PMID 38983511, 2022). "CD25+FoxP3+ Treg, FoxP3+TIGIT+ Treg, and FoxP3+T-bet+ Treg were also observed to increase as disease resolved in patients with active uveitis." (PMID 29774027, 2018). "The number of TIGIT+FoxP3+ Tregs was significantly decreased in PBMCs from patients with uveitis." (PMID 35720417, 2022). "More specific suppressive Treg markers such as TIGIT and PD-1 may also be valuable in establishing a correlation between Treg level and uveitis resolution." (PMID 38983511, 2022). "A study involving 50 AU patients and 10 healthy subjects revealed that there were significantly higher frequencies of CD4+CD25+FoxP3+ Treg, TIGIT+ Treg, and T-bet+ Treg and Treg/Th1 ratio in the clinical remission subjects compared with active patients of uveitis." (PMID 35720417, 2022). "In summary, our data show that CD4+ T-cells in chronic relapsing, remitting sight-threatening non-infectious uveitis deviate toward the Th1 type and that Treg with upregulated levels of T-bet and TIGIT expression are associated with disease remission." (PMID 29774027, 2018). "However, our results suggest that low levels of TIGIT may be a biomarker for increased risk of disease relapse in sight-threatening non-infectious uveitis." (PMID 29774027, 2018). "Results further showed that TIGIT+FoxP3+ Tregs are induced by stimulation of adenosine 2A receptor (A2Ar) in healthy volunteers, but not in patients with uveitis." (PMID 35720417, 2022). "Our data show that hypomethylation at FOXP3 TSDR, FOXP3 promoter, and TIGIT CpG sites and higher levels of TIGIT+ Tregs are associated with clinical remission, and may have value in determining remission, of relapsing and remitting sight-threatening non-infectious uveitis." (PMID 29774027, 2018). "Clinical remission of sight-threatening non-infectious uveitis has an immunoregulatory phenotype characterized by upregulation of peripheral Treg, polarized toward T-bet and TIGIT." (PMID 29774027, 2018). "However, the expression of the co-inhibitory molecule TIGIT by Treg from patients in sustained clinical remission of disease, who are no longer on therapy, has not been previously investigated in uveitis." (PMID 29774027, 2018).
asthma (3 papers, 2017 to 2021). "Our results indicate that the selective inhibitory effects of DW2008S on Th2 responses may result from the regulation of TIGIT+ Th2 cell number in mice with asthma." (PMID 29512870, 2018). "The expression levels of CD28, CD59, LAG3, TCRab and TIGIT were higher, while CD45, CD45RO, RORγ, OX40 and Tbet lower in cluster 16 in acute pneumonia, stable pneumonia, acute asthma and stable asthma." (PMID 34841705, 2021). "One study comparing PBMC methylation changes of 97 inner-city children with persistent atopic asthma to 97 healthy controls found 81 differentially methylated regions, including hypomethylated immune genes in asthma (i.E. il13, RUNX3, TIGIT)." (PMID 28774304, 2017). "Epigenomic studies have identified methylation patterns specific to COPD (e.g., C10orf11 in lung), asthma (e.g., IL13, RUNX3, TIGIT in PBMCs) and IPF (e.g., CASZ1 in lung), although much work remains to characterize cell-specific changes and include more ARDS and PAH samples." (PMID 28774304, 2017).
atherosclerosis (3 papers, 2013 to 2024). A disease characterized by the build-up of fatty material and calcium deposition in the arterial wall resulting in partial or complete occlusion of the arterial lumen. "Whereas agonistic anti-TIGIT treatment reduced T cell proliferation, dendritic cells which are also involved in the pathogenesis of atherosclerosis were elevated in these mice." (PMID 24376654, 2013). "In the present study, we used an agonistic anti-TIGIT antibody to determine the effect of excessive TIGIT-signaling on atherosclerosis." (PMID 24376654, 2013). "To determine whether the TIGIT-mediated impairment of T cell function affects the development of early atherosclerosis (4 weeks of Western type diet), we measured atherosclerotic lesion sizes upon agonistic anti-TIGIT treatment." (PMID 24376654, 2013). "Future research should concentrate more on the role of TIGIT-PVR signaling, since the generation of tolerogenic DCs in combination with intrinsic T cell inhibition possibly does affect atherosclerosis." (PMID 24376654, 2013). "In addition to the co-expression of TIGIT and TIM-3 on Tregs, studies have also shown that the co-expression of PD-1 and TIM-3 on CD8+ T cells is upregulated in patients with atherosclerosis." (PMID 39926714, 2024). "In conclusion, we showed that although triggering of the TIGIT pathway decreases proliferation and activation of splenic T cells both in vitro and in vivo, it does not affect atherosclerosis development and local T cell numbers." (PMID 24376654, 2013). "Despite the inhibition of splenic T cell responses, agonistic anti-TIGIT treatment does not affect initial atherosclerosis development, possibly due to increased activity of dendritic cells." (PMID 24376654, 2013). "Meanwhile, atherosclerosis-driven dysfunctional/plastic interferon- γ (IFNγ) +C-C motif chemokine receptor 5 (CCR5) + Th1-Tregs in ApoE−/− mice show reduced TIGIT expression, suggesting that TIGIT plays a stabilizing role in Tregs, helping to suppress inflammation." (PMID 39926714, 2024). "To date, the role of the coinhibitory TIGIT-PVR axis in atherosclerosis has not been explored." (PMID 24376654, 2013).
bladder tumors (3 papers, 2019 to 2026). "Surprisingly, in the subcutaneous tumor model, administration of a-TIGIT did not achieve better effects than injection of a-PD-1; we speculated that this was because only the bladder tumor microenvironment exhibited a higher expression of TIGIT." (PMID 35069212, 2021). "TIGIT is an inhibitory receptor expressed on T cells and natural killer cells and regulates anti-tumor immunity through competition with CD226 for binding to CD155, and increased expression of TIGIT in bladder tumors is associated with impaired effector function." (PMID 41590518, 2026). "Findings from our study provide compelling evidence for co-expression of multiple immune checkpoint genes including, PD-1, PD-L1, IDO1, TIGIT, TIM-3, TGFB1, LAG3, and others, that potentially contribute to compensatory immune evasion in bladder tumors." (PMID 31174611, 2019).
diabetes (3 papers, 2020 to 2025). "Partial inhibition of PD1-PDL1 in combination with TIGIT inhibition resulted in rapid diabetes in NOD mice." (PMID 38533515, 2024). "However, blocking PD1 signaling increased CD226 and TIGIT co-expressing cells, and TIGIT inhibition led to rapid diabetes in NOD mice." (PMID 38533515, 2024). "However, TIGIT restrained these stem-like memory T cells in the islets when PD1 signaling was reduced, resulting in rapid diabetes when TIGIT is blocked." (PMID 38533515, 2024). "TIGIT HET and KO females and males showed similar diabetes incidence to WT littermates." (PMID 33013915, 2020). "TIGIT blockade did not induce autoimmune diabetes, while PDL1 inhibition resulted in rapid diabetes onset in NOD mice." (PMID 38533515, 2024).
graft versus host disease (3 papers, 2013 to 2022). An immune system disorder that occurs after allogeneic hematopoietic stem cell transplant and is a reaction of donor immune cells against host tissues. "In transplantation immunity, TIGIT can regulate the severity of graft-versus-host disease (GVHD) by affecting the function of Treg cells and the number of donor antigen-reactive T cells." (PMID 36426354, 2022). "Pharmacological TIGIT activation has shown potential to ameliorate murine graft versus host disease (GVHD)." (PMID 35410311, 2022).
head and neck cancer (3 papers, 2022 to 2025). A primary or metastatic malignant neoplasm affecting the head and neck. "Nevertheless, as multiple clinical trials investigating different TIGIT antibodies are ongoing, we will obtain comprehensive data in the future in order to determine which TIGIT antibody acts most efficiently in head and neck cancer patients and even more in the subgroup of OSCC." (PMID 36551992, 2022).
kidney cancer (3 papers, 2023 to 2025). Primary or metastatic malignant neoplasm involving the kidney. "TIGIT plays a dual role in immune resistance, as it restricts adaptive and innate immunity against malignancies, like lung and kidney cancers." (PMID 39064019, 2024). "Higher expression of LAG3, PDCD1, and TIGIT showed the worst survival outcome of anti-ICB therapy in kidney cancer indication drug resistance, whereas high LAG3 and CXCL13 expressions were associated with better survival of anti-PDL1 therapy in metastatic BLCA, indicating drug sensitivity." (PMID 40076932, 2025). "We first systematically analyze the relationship between TIGIT and a variety of cancers, especially kidney cancer, and discovered that the expression of TIGIT was quite high in KIRC, but not KICH and KIRP, and was associated with poor prognosis." (PMID 37035135, 2023).
liver cirrhosis (3 papers, 2020 to 2023). "We found significantly higher expression of markers of T-cell senescence (e.g., PTPRC, TIGIT, and TNF) and exhaustion (e.g., PDCD1, CTLA4, LAG3, and TNFRSF9) in hepatic CD4+ and CD8 + T cells in participants with NASH or liver cirrhosis than in controls." (PMID 37735474, 2023). "Genes related to senescence (e.g., PTPRC, TIGIT, and TNF) and exhaustion (e.g., PDCD1, CTLA4, LAG3, and TNFRSF9) were highly enriched in CD4+ and CD8 + T cells from the participants with liver cirrhosis." (PMID 37735474, 2023).
liver disease (3 papers, 2023 to 2024). "Importantly, T cell exhaustion is associated with liver disease prior to HCC formation, mediated in part by LSEC, indicating the potential of targeted interventions, such as co-immunotherapy with PD-1 and TIGIT, for those affected by chronic liver disease." (PMID 39896805, 2024). "Tim3 and TIGIT have been reported as NK cell exhaustion markers in hepatic diseases." (PMID 38107019, 2023).